IL10 (interleukin 10)
Diseases named in the same sentence as IL10 in open-access papers (continued):
Sharing a sentence is not in itself a finding about the gene and the disease.
bacteremia (79 papers, 2010 to 2026). "In the present study, we examined the transcriptome, DNMT3A genotype and IL-10 proteome of whole peripheral blood to differentiate immune response pathways associated with RB versus PB outcomes in clinical MRSA bacteremia." (PMID 38846955, 2024). "As previously reported, early elevation of IL-10 in G- bacteremia was associated with poor prognosis." (PMID 36544765, 2022). "Interleukin-10 has been investigated as a potentially valuable biomarker for risk stratification in pediatric febrile neutropenia, particularly in identifying children at elevated risk for bacteremia and severe infections." (PMID 40647525, 2025). "The heightened IL-10 levels with Sa exposure/vaccination are particularly intriguing due to the strong association of IL-10 with Sa colonization, biofilm formation, reinfection, and mortality in bacteremia." (PMID 39680460, 2024). "Collectively, these results allow us to hypothesize that the persistence of bacteremia may be the cause of increased IL-10 production in the host’s immune cells." (PMID 39770719, 2024). "TLR2 downregulation and IL-6 and IL-10 concentrations suggestive of immune dysregulation during early bacteremia may be associated with mortality from SAB." (PMID 33256638, 2020). "It is unknown if high (anti-inflammatory) IL-10 levels observed in the present study are associated with the decreased leukocyte counts and neutropenia observed during high bacteremia; among other hematological alterations, leukocytosis and neutrophilia are characteristics of inflammation." (PMID 26403079, 2015). "IL-10 provides reliable bacteremia exclusion when combined with PCT (89% specificity, 100% NPV; Doerflinger 2021), with PCT achieving AUC 0.842 and IL-10 AUC 0.826 as standalone biomarkers (Doerflinger 2021)." (PMID 40647525, 2025). "The model outperformed clinical variables, and IL-10 levels declined 5-fold by Day 2 in bacteremia, suggesting therapeutic monitoring utility." (PMID 40647525, 2025). "IL-10 provides reliable bacteremia exclusion when combined with PCT (89% specificity, 100% NPV), while PCT alone achieved AUC 0.842 and IL-10 alone AUC 0.826 (Doerflinger 2021)." (PMID 40647525, 2025). "IL-10 concentrations were higher in patients with high bacteremia scores than those with low bacteremia scores 4–9 days prior to the last positive culture day (p < 0.05)." (PMID 38969796, 2024). "The level of IL-10 was significantly increased in the plasma of patients with a high Pitt bacteremia score and those who died within 12 weeks from the index day." (PMID 38969796, 2024). "The IL-10 concentration in the early stage of bacteremia can be a predictive factor of poor clinical outcomes of persistent bacteremia." (PMID 38969796, 2024). "In bacteremia, IL-6 and IL-10 were more positive than PCT and CRP, and IL-6 and IL-10 were significantly more specific than PCT in the diagnosis of diagnostic G- bacteremia." (PMID 39559703, 2024). "The IL-10 concentration was high in the early phase of bacteremia in patients with high Pitt bacteremia scores and those who died within 12 weeks from the index day." (PMID 38969796, 2024). "The specificity of IL-6 and IL-10 was significantly higher than that of PCT in the diagnosis of G- bacteremia." (PMID 39559703, 2024). "The plasma concentration of IL-10 4–8 days before the last positive blood culture day was significantly higher in patients with high bacteremia scores and patients who died within 12 weeks from the index day." (PMID 38969796, 2024). "To evaluate the predictive capacity of T and B cell hub gene expression and IL-10 cytokine levels for predicting outcome of MRSA bacteremia, we built a random forest classification model based on these 41 variables." (PMID 38846955, 2024).
bacteremia (continued). "A significant decrease in TNFα, IL-1β, and IL-8 production was observed in patients with documented bacteremia (p value < 0.05), and a significant increase in IL-10 was also detected (p value < 0.05)." (PMID 39559359, 2024). "Confirming our findings, IsdB vaccination of Sa-exposed hosts, followed by a high dose of Sa, led to elevated serum IL-10 levels in a murine model of severe bacteremia." (PMID 39680460, 2024). "The vital function of IL-10 in Bartonella’s immune evasion has been demonstrated in mouse models, as the pathogen B. birtlesii is unable to establish bacteremia in IL-10 knockout mice." (PMID 37362930, 2023). "These plasma concentrations of IL-10 remained similarly elevated in the sham and splanchnic-denervated groups from 25-to-30-h of bacteremia." (PMID 37535121, 2023). "IL-10 concentrations observed in the present study (median: 13 pg/mL) were comparable to published data in patients with S. aureus bacteremia (median: 10–20 pg/mL)." (PMID 36275812, 2022). "In this study, we observed peak concentrations of IL-10 during bacteremia suggestive of an anti-inflammatory response dominated by IL-10, which likely links to low TNF production levels during bacteremia." (PMID 35925895, 2022). "Separately for MRSA bacteremia, there were 81 patients who had Day 1 measurements of either IL-10 and/or TNF." (PMID 33820537, 2021). "In contrast, patients with S. aureus bacteremia presented significantly elevated IL-10, IFN-γ, PTX3 and TNF-α levels compared to IC (other) patients." (PMID 33535593, 2021). "Transnasal inoculation of S. pneumoniae in combination with IL-10 resulted in impaired bacterial clearance from the lungs, bacteremia and early lethality in mice." (PMID 34589087, 2021). "In line with our experimental observations, a distinctively higher ratio (1.6 ± 0.77) for IFN/IL10 in SIRS patients was observed compared to patients with bacteremia (0.8 ± 0.88)." (PMID 33767693, 2021). "For IL-10, an increase of serum levels with pronounced bacteremia was also detectable in two of three piglets: piglet H2 showed an increase up to 1.6 ng/mL at 19 hpi." (PMID 31947746, 2020). "Sources of bacteremia, median Pitt bacteremia scores, Charlson comorbidity indices, and median IL-10 serum concentrations were similar in both groups." (PMID 30858203, 2019). "Serum drawn on the first day of bacteremia was sent to a reference laboratory post hoc for measurement of interleukin-10 (IL-10) concentrations and correlation to in-hospital mortality." (PMID 30858203, 2019). "It was found that the fungal sepsis is associated with substantial increase in all cytokines levels (TNF-α, IL-1β, IL-4, IL-6, and IL-10), when compared with bacterial sepsis." (PMID 28367457, 2017). "This study was conducted prospectively to evaluate the potential of interleukin (IL)-6, IL-8, and IL-10 for predicting bacteremia and to compare the levels of IL-6, IL-8, and IL-10 between patients during infection and patients after treatment." (PMID 28148470, 2017). "Alternately, polysaccharides isolated from AM have recently been shown to suppress Treg function by downregulating the production of IL-10 in a murine model of bacterial sepsis." (PMID 27190535, 2016). "In previous reports, particularly the pro-inflammatory cytokine IL-6 and the anti-inflammatory cytokine IL-10 have been positively correlated to different markers of severity such as mental confusion, hypotension, pleural effusion, and bacteremia." (PMID 26407163, 2015). "IFN-γ (Th1) and IL-10 (anti-inflammatory) mRNA levels varied significantly over time in both groups with higher values at times of maximal bacteremia compared to values early after M. haemofelis exposure (indicated by arrows)." (PMID 26403079, 2015). "Mice deficient in the expression of CD40 have been shown to have improved survival during bacterial sepsis as a result of decreased induction of IL-6, IL-10, IL-12 and IFNγ expression." (PMID 21949840, 2011).
bacteremia (continued). "To better understand the mechanism linking IL-10 levels to outcomes in MRSA bacteremia, we determined the relationship between identified hub genes in the B and T cell enriched signaling modules (ME7 and ME2 respectively), IL-10 cytokine levels and DNMT3A genotype." (PMID 38846955, 2024). "(2016) analyzed 3023 samples (2819 fever case samples and 204 control samples) and found that the positivity rates of interleukin-6 (IL-6) and IL-10 in children with bacteremia were 92.8% and 82.2%, respectively, which were higher than those of PCT (33.8%) and CRP (73.1%)." (PMID 39559703, 2024). "Furthermore, transcriptional profiles correlated with lower IL-10 cytokine level and heterozygous DNMT3A A/C genotype, both of which have been associated with reduced risk of PB outcome in human MRSA bacteremia." (PMID 38846955, 2024). "At 23-h of bacteremia, there was also an increase in the plasma concentrations of the anti-inflammatory cytokine, IL-10, in both the sham (from 0.44 ± 0.17 to 1.72 ± 0.51 ng/mL, P = 0.014) and splanchnic-denervated groups (from 0.50 ± 0.14 to 1.56 ± 0.36 ng/mL, P = 0.033)." (PMID 37535121, 2023). "In conjunction with the data obtained in this study, IL-10 may thus be a valuable marker for a variety of infections, not only S. aureus bacteremia, and may potentially aid in clinical diagnosis finding." (PMID 36275812, 2022). "For instance, it was recently reported that during the early stages of Staphylococcus aureus bacteremia, increased levels of IL-10 are related to persistent bacteremia and higher mortality, while increased levels of IL-1β, after three to seven days of antibiotic therapy, are related to survival." (PMID 35563218, 2022). "Among the Th-2 cytokines, IL-10 and IL-4 were significantly elevated in candidemia patients compared to healthy controls, but only IL-10 was significantly elevated in candidemia compared to bacteremia groups." (PMID 34684298, 2021). "Longitudinal analyses by LMM revealed that TNF-α, IL-6, and IL-10 concentrations were significantly increased in SAB patients who died within 30 d post-bacteremia (with SAB patients who survived as reference) (p = 0.001, p = 0.002, and p < 0.001, respectively)." (PMID 33256638, 2020). "Consistent with the literature, in this study, patients who died from SAB had significantly higher IL-6 and IL-10 levels during early-stage bacteremia, and patients who died within 7 days of SAB onset further displayed a significantly elevated IL-10/TNF-α ratio and TLR2 downregulation." (PMID 33256638, 2020). "We could detect an induction of IL-6 and the anti-inflammatory mediator IL-10 in serum of intravenously S. suis-infected piglets (after 13–19 hpi) that showed a pronounced bacteremia." (PMID 31947746, 2020). "The observed in vivo induction of IL-6 and IL-10 in bacteremic pigs raises the question of whether the induction of pro-inflammatory cytokines also has protective properties in bacteremia." (PMID 31947746, 2020). "Among the cytokines produced during severe bacteremia, IL-10 acts as an immunoregulatory molecule." (PMID 33237133, 2020). "As we observed an induction of IL-6 and IL-10 in piglets with pronounced bacteremia, we tested whether cytokine induction could be reproduced in a whole-blood assay upon addition of viable S. suis, as has been demonstrated previously." (PMID 31947746, 2020). "In this context, it has been shown that IL-10 impairs neutrophil recruitment to infected tissues in a neonatal mouse model of bacterial sepsis, and that perturbing IL10 induction resulted in the rescue of efficient neutrophil recruitment, bacterial clearance, and increased survival." (PMID 29881380, 2018). "Thus, the high IL-10 transcription levels observed at times of high bacteremia would be consistent with the high serum protein, γ-globulin and anti-M." (PMID 26403079, 2015).
bacteremia (continued). "The study highlighted the superiority of PCT (AUC = 0.842) and IL-10 (AUC = 0.826), with their combination achieving 100% sensitivity and 89% specificity—identifying 80% of episodes (n = 79) as low risk without missing bacteremia." (PMID 40647525, 2025). "However, reflecting the complexity of the immune response/biological processes occurring in bacteremia patients, not only pro-inflammatory- but also anti-inflammatory- pathways e.g. interleukin-10 signaling were enriched within the differentially expressed proteins." (PMID 41298591, 2025). "Indeed, reported IL-10 cutoffs in pediatric FN range widely—from 4.37 pg/mL to 100 pg/mL—with lower thresholds (e.g., 4.37 pg/mL) favoring sensitivity for bacteremia detection when combined with PCT, and higher thresholds (e.g., 100 pg/mL) offering better specificity for severe infections." (PMID 40647525, 2025). "Furthermore, Tamarixetin, is a derivative of quercetin, and it has shown anti-inflammatory effects during bacterial sepsis mouse models via increased production of IL-10-secreting cells in the spleen and thus an increased production of anti-inflammatory cytokine IL-10." (PMID 39126050, 2024). "However, the IL-10 excess may induce immunosuppression in bacterial sepsis and increases mortality in P-CAP due to bacterial clearance impairment." (PMID 38143267, 2023). "Furthermore, we associated IFNγ/IL10 to the bacterial load in critical ill patients, and compared publically available data of patients with and without bacteremia." (PMID 33767693, 2021). "Patients with MRSA bacteremia, septic shock, Pitt bacteremia score of ≥4, and a quartile 4 IL-10 response (> 31.13 pg/ml) were 5 times more likely to die (OR 6.39, 95% CI 1.11, 36.74) compared to those with similar clinical characteristics who had a quartile 2 IL-10 response (5.15–13.57 pg/ml)." (PMID 33820537, 2021). "The positive correlations between IL-10 and the presence of this specific pair of clinical phenotypes infers a link between immune modulation and more complicated MRSA bacteremia." (PMID 39966757, 2025). "Early response cytokines (i.e. first wave at initiation of bacteremia) included IFN-γ, IL-1β, IL-6, IL-18, IL-1ra, IL-10, IL-12 (p40), IL-17a and MCP-1, which all reached peak levels during bacteremia." (PMID 35925895, 2022). "Recently, cytokine analysis demonstrated that interleukin (IL)-6, IL-10, and Tumor Necrosis Factor-α (TNF-α) were significantly elevated in pediatric hematology patients with G- bacteremia." (PMID 36544765, 2022). "Therefore, it has been hypothesized that the high IL-10 levels observed during maximal bacteremia in M. haemofelis-infected cats in a previous study might limit the inflammatory response to M. haemofelis and potentially prevent the clearance of these organisms." (PMID 26403079, 2015). "Cytokines and chemokines, including IL-6, IL-10, IL-17A, and MIP-2 were induced systemically and in the lungs of rats with S. aureus bacteremia." (PMID 25978669, 2015). "However, in the context of bacteremia, recent work has found that elevated IL-17A is correlated with APMB and mortality, especially when paired with IL-10 levels." (PMID 39966757, 2025). "It is significant that, unlike previous studies, we measured IL-6 and IL-10 concentrations serially throughout the bacteremia period." (PMID 38969796, 2024). "Our study revealed that the cytokines IL-2, IL-6 and IL-10 were significantly higher in candidemia patients than in bacteremia patients, which was not reported in previous studies." (PMID 34684298, 2021). "In contrast, no increase in IL-6 or IL-10 levels was detectable in the sera of three pigs, which were able to control bacteremia, as well as in the three uninfected control pigs." (PMID 31947746, 2020). "When comparing viremia and fungemia (P = 0.50), bacteremia and fungemia (P = 0.50) and bacteremia and viremia (P = 0.31), no significant changes in IL-10 serum concentration were found after Bonferroni correction (adjusted α = 0.0083)." (PMID 26315105, 2015).
bacteremia (continued). "The second bacteremia peak also trended toward higher bacterial densities in the wild-type B-1 cell transferred group than in the IL-10−/− B-1 cell transferred group, but the differences were not statistically significant (p<0.11)." (PMID 20625435, 2010). "Additionally, elevated IL-10 is largely observed in patients with more severe disease and higher mortality, which are undesirable outcomes in a sublethal NHP model of MRSA bacteremia." (PMID 40766078, 2025). "Interestingly, splanchnic denervation at 24-h of bacteremia did not significantly affect IL-10 levels." (PMID 37535121, 2023). "Using the clinical model which included Pitt bacteremia score ≥ 4 and septic shock (AUC = 0.801, 95% CI 0.690, 0.912), and quartile 2 as the reference group, the addition of Day 4 IL-10 quartiles (p = 0.03), but not Day 4 TNF quartiles (p = 0.07), significantly improved model performance." (PMID 33820537, 2021). "IL-6 and IL-10 levels were significantly higher in non-survivors than in survivors on days 2–5 post-bacteremia (P = 0.010 and P = 0.021, respectively), and those dying within 7 d of SAB (n = 3) displayed significantly higher IL-10/TNF-α ratios than the survivors did (P = 0.007)." (PMID 33256638, 2020). "Besides, the levels of IL-6, IL-8, and IL-10 in bacterial sepsis nonsurvivors and the levels of IL-6 and IL-10 in SARS-CoV-2 sepsis nonsurvivors were higher when compared with the corresponding survivors." (PMID 33329592, 2020). "Despite no bacteremia in all groups (data not shown), serum IL-1β, IL-6, and TNF-α (but not IL-10) were increased in the infected mice from both bacterial strains." (PMID 35955437, 2022). "Using a definition of ≥4 days, our current study identified IL-10 and TNF quartiles, but not IL-17A, measured on Day 1 to be the most predictive for persistent bacteremia." (PMID 33820537, 2021). "Similar to that observed in patients with persistent bacteremia, non-survivors with measured cytokine response on Day 4 of bacteremia significantly differed from survivors in overall TNF, IL-10 and IL-8 response." (PMID 33820537, 2021). "Inclusion of either IL-10 (AUC 0.873) or TNF (AUC 0.879) quartiles, but not both, measured on Day 4 to the significant clinical predictors (coronary artery disease, Pitt bacteremia score ≥ 4, and septic shock) improved model performance for mortality." (PMID 33820537, 2021). "An increase in IL-6 and IL-10, but not in IFN-γ or IL-17A, was observed in two of three piglets with pronounced bacteremia 16 to 20 h after infection, but not in piglets with controlled bacteremia." (PMID 31947746, 2020).